ENSG00000269035 (novel protein)
Gene: Protein-coding gene on chromosome 19 (17,436,611 to 17,460,804, reverse strand). Ensembl gene ENSG00000269035.
Genetic constraint (gnomAD): Loss-of-function variants: 14 observed, 10.6 expected, observed/expected ratio (o/e) 1.32, 90% interval 0.86 to 1.87. Missense variants: 298 observed, 257.18 expected, observed/expected ratio (o/e) 1.16, 90% interval 1.05 to 1.27. Synonymous variants: 124 observed, 105.52 expected, observed/expected ratio (o/e) 1.18, 90% interval 1.01 to 1.36.